HOXA10 (homeobox A10)
Diseases named in the same sentence as HOXA10 in open-access papers (continued):
Sharing a sentence is not in itself a finding about the gene and the disease.
metastatic disease (2 papers, 2016 to 2022). "We found seven DEGs (CCND1, EGFR, ENTPD5, HOXA10, IGF1R, MYC, and SNAI2) related to metastatic disease." (PMID 35806108, 2022). "HOXA10 is methylated in differentiated CD24-positive normal mammary cells and luminal BC cells, and the methylation level increases during the progression of BC from DCIS via a primary invasive ductal carcinoma, to a metastatic tumor." (PMID 27993161, 2016).
myeloproliferative disorder (2 papers, 2014 to 2018). A clonal hematopoietic stem cell disorder, characterized by proliferation in the bone marrow of one or more of the myeloid (i.e., granulocytic, erythroid, megakaryocytic, and mast cell) lineages. "In murine bone marrow transplantation studies, HOXA10 overexpression induces a myeloproliferative disorder with accumulation of mature phagocytes in the peripheral blood and tissues." (PMID 25307539, 2014). "Moreover, overexpression of HOXA10 in murine bone marrow induces a myeloproliferative disorder characterized by expansion of the committed myeloid progenitor population (common granulocyte/monocyte progenitors or GMP)." (PMID 25307539, 2014).
myocardial hypertrophy (2 papers, 2021 to 2024). "Elevated levels of Hoxa10 have been shown to counteract the electrical remodeling effects and myocardial hypertrophy induced by Ang II in cardiac cells." (PMID 39564110, 2024). "Taken together, our results revealed miR-27a-3p/Hoxa10/Kv4.3 axis as a new mechanism of Ang II-induced cardiomyocyte hypertrophy, which provided a new target for clinical prevention and treatment of cardiac hypertrophy and heart failure." (PMID 34248630, 2021). "We firstly demonstrated that miR-27a-3p/Hoxa10 axis was involved in myocardial hypertrophy and electrical remodeling." (PMID 34248630, 2021). "Further studies showed that miR-27a-3p binded to 3′UTR of Hoxa10 which was down-regulated in cardiac hypertrophy." (PMID 34248630, 2021). "Collectively, miR-27a-3p and Hoxa10 are involved in cardiac hypertrophy and electrical remodeling induced by Ang II, and the reversal of this process was closely related to targeting miR-27a-3p, Hoxa10 and Kv4.3." (PMID 34248630, 2021). "Although some studies have found that Hoxa10 was closely associated with the occurrence and development of cardiovascular diseases, there are no reports about its implication in myocardial hypertrophy and electrical remodeling." (PMID 34248630, 2021). "The overexpression of Hoxa10 could reverse cardiac hypertrophy and electrical remodeling by targeting Kv4.3 protein." (PMID 34248630, 2021). "Our research demonstrated that the overexpression of Hoxa10 can reverse the expressions of hypertrophy-related genes and electrical remodeling, which is the first time to report the correlation between Hoxa10 and myocardial hypertrophy at home and abroad." (PMID 34248630, 2021). "Therefore, the pathway involving miR-27a-3p, Hoxa10, and Kv4.3 represents a newly discovered regulatory mechanism crucial to myocardial cell hypertrophy triggered by Ang II, providing a novel target for the clinical strategies aimed at preventing and treating cardiac hypertrophy and HF." (PMID 39564110, 2024). "Therefore, our results revealed for the first time that the miR-27a-3p/Hoxa10/Kv4.3 axis is involved in the pathogenesis of myocardial hypertrophy and electrical remodeling, and these results provided a new therapeutic strategy for myocardial hypertrophy and electrical remodeling clinically." (PMID 34248630, 2021). "In order to confirm whether Hoxa10 was involved in myocardial hypertrophy process." (PMID 34248630, 2021). "The limitations of our study are as followings: first of all, we only discussed myocardial hypertrophy and electrical remodeling from the miR-27a-3p/Hoxa10/Kv4.3 axis, but did not further study myocardial regeneration and myocardial fibrosis." (PMID 34248630, 2021).
seminoma (2 papers, 2018 to 2022). A radiosensitive malignant germ cell tumor found in the testis (especially undescended), and extragonadal sites (anterior mediastinum and pineal gland). "In contrast, cytoplasmic HOXA10 was mainly expressed in testicular cancer cells (HScore = 1.40 + 0.06 in seminoma, 1.67 + 0.167 in spermatocytic tumor and 1.45 + 0.13 in non-seminoma), but less commonly in benign testis (HScore = 0.28 + 0.07)." (PMID 30581773, 2018). "Since seminoma accounts for approximately half of testicular cancers, we used the TCam2 testicular seminoma cell line as a model to further characterize HOXA10 transcriptome in testicular cancer cells." (PMID 30581773, 2018). "In this study, we report that HOXA10 is expressed in the nucleus of benign spermatocytes and frequently loses its nuclear localization in TGCTs including both seminoma and non-seminoma." (PMID 30581773, 2018). "While highly expressed in spermatocytes of benign testes (HScore = 1.98 + 0.15), all cancerous testes had extremely low or no nuclear HOXA10 expression with HScores = 0.067 + 0.019 in seminoma, 0.207 + 0.06 in spermatocytic tumor, and 0 in non-seminoma." (PMID 30581773, 2018). "HOXA10 has been shown to be expressed and localized in the nuclei of spermatocytes in normal tissues, while it is often dislocated in TGCT cells, both seminomas and non-seminomas." (PMID 36230984, 2022). "To study the expression of HOXA10 in testicular tumors, we applied IHC on a tissue microarray (TMA), containing 5 benign, 96 seminoma, 8 spermatocytic tumor and 17 non-seminoma." (PMID 30581773, 2018).
testicular cancer (2 papers, 2018 to 2023). A primary or metastatic malignant neoplasm that affects the testis. "Together, these results indicate that loss of nuclear expression of HOXA10 is associated with testicular cancers." (PMID 30581773, 2018). "Nevertheless, the expression pattern between tumor cells and in vitro cell models support that loss of nuclear function of HOXA10 is associated with testicular cancer." (PMID 30581773, 2018). "Reduced nuclear expression and increased cytoplasmic expression of HOXA10 are associated with testicular cancers." (PMID 30581773, 2018). "To study the cellular functions of HOXA10 in testicular cancer cells, we used three available TGCT cell lines, TCam2, NT-2, and NCCIT." (PMID 30581773, 2018). "Enhanced HOXA10 expression in testicular cancer cell models inhibits cell proliferation and delays cell cycle progression through G2/M phases." (PMID 30581773, 2018). "Intervention: Immunohistochemistry and immunofluorescence were performed to measure the expression and cellular localization of HOXA10 in testicular cancer tissues and cell models." (PMID 30581773, 2018). "HOXA10 transcriptomes were profiled with Ampliseq RNA-seq in testicular cancer cells." (PMID 30581773, 2018).
uterine fibroids (2 papers, 2013 to 2022). "Rackow and Taylor investigated the effect of uterine leiomyomas on these markers of endometrial receptivity HOXA10 and HOXA11." (PMID 24639724, 2013).
vitamin D deficiency (2 papers, 2021 to 2024). A nutritional condition produced by a deficiency of VITAMIN D in the diet, insufficient production of vitamin D in the skin, inadequate absorption of vitamin D from the diet, or abnormal conversion of vitamin D to its bioactive metabolites. "HOXA10 expression was significantly lower only in young women in the vitamin D deficiency group." (PMID 39829955, 2024). "However, the specific mechanism by which vitamin D deficiency affects HOXA10 expression and subsequently impacts embryo implantation remains unclear." (PMID 39829955, 2024). "Expression of HOXA10 in endometrial tissue from women undergoing IVF with or without vitamin D deficiency." (PMID 39829955, 2024).
acute lymphoblastic leukemia (1 paper, 2010). Leukemia with an acute onset, characterized by the presence of lymphoblasts in the bone marrow and the peripheral blood. "Another group of T-cell acute lymphoblastic leukemia (T-ALL)-associated oncogenes are homeobox genes and includes members of the NK-like family, TLX1/HOX11, TLX3/HOX11L2 and NKX2-5/CSX, and of the clustered homeobox genes, HOXA5, HOXA9, HOXA10 and HOXA11." (PMID 20565746, 2010).
anencephaly (1 paper, 2019). A rare neural tube defect during pregnancy, resulting in the absence of a large portion of the brain and skull in the fetus. "Notably, the expression of HOXA10 genes was negatively correlated with CUL4B levels in human anencephaly NTD cases." (PMID 30992047, 2019). "Notably, the expression of HOXA7, HOXA10, and HOXB7 genes was negatively correlated with CUL4B levels in human anencephaly NTD cases." (PMID 30992047, 2019). "To investigate the potential effect of expression levels of the selected HOX genes (HOXA1, HOXA7, HOXA9, HOXA10, HOXB1, and HOXB7) in anencephaly, we evaluated 10 anencephaly cranial tissues and 10 matched normal fetus cranial samples by the NanoString technique." (PMID 30992047, 2019).
carcinoma of the lip (1 paper, 2022). "HOXA5, HOXB9, HOXC8, HOXC10, and HOXC11 genes were specific to certain sites of the oral cavity whereas HOXA10 was associated with the development of the carcinoma of the lip and oral cavity." (PMID 35710803, 2022).
Duchenne muscular dystrophy (1 paper, 2025). Duchenne muscular dystrophy (DMD) is a neuromuscular disease characterized by rapidly progressive muscle weakness and wasting due to degeneration of skeletal, smooth and cardiac muscle. "In a Duchenne muscular dystrophy (DMD) model (mdx mice), HOXA10 deficiency resulted in systemic muscle atrophy (except in the head)." (PMID 40141276, 2025).
endometritis (1 paper, 2024). An acute or chronic, usually bacterial infectious process affecting the endometrium. "Women with and without endometritis had lower HOXA10 andHOXA11 expression values than women in the controlgroup (fertile women without endometritis)." (PMID 38801313, 2024).
Hernia (1 paper, 2020). "In this study, HOXC10 was downregulated in animals affected with scrotal hernia and, although it has not yet been associated with hernias, the HOXA10 gene, which belongs to the same gene family, has already been considered a candidate for causing this pathology." (PMID 31973088, 2020).
high-grade glioma (1 paper, 2017). "HOXA9 and HOXA10 genes were associated with a shorter survival in pediatric high-grade glioma patient samples, while elevated HOXA9 and HOXA10 gene methylation was associated with an increased survival probability." (PMID 28055976, 2017).
hypothyroidism (1 paper, 2021). Abnormally low levels of thyroid hormone. "The results show that hypothyroidism impaired uterine receptivity by decreasing the level of E2 as well as decreasing the expression of the uterine-receptivity factors homeobox A10 and osteopontin." (PMID 34573602, 2021). "The results show that hypothyroidism impairs uterine receptivity by decreasing the level of E2 as well as the expression of the uterine-receptivity factors HOXA10 and OPN." (PMID 34573602, 2021). "A article proved that, in rats with PTU-induced hypothyroidism, the E2 level as well as the expression of the uterine-receptivity factors homeobox A10 and osteopontin was decreased." (PMID 34573602, 2021). "Furthermore, in our experiment, in the groups of animals with PTU-induced hypothyroidism, the levels of homeobox A10 (HOXA10/HOXA10) and osteopontin (OPN/OPN), which are considered to be uterine receptivity markers, were significantly lower in comparison to those in the control group." (PMID 34573602, 2021).
lymph node metastasis (1 paper, 2021). "In this study, we demonstrated HOXA10 was upregulated in GC patients and the difference was even more pronounced in patients with lymph node metastasis (LNM) than without." (PMID 33563300, 2021).
lymphoma (1 paper, 2020). A malignant (clonal) proliferation of B- lymphocytes or T- lymphocytes which involves the lymph nodes, bone marrow and/or extranodal sites. "Interestingly, we found that HOXA10 had the most reduction in lymphoma cell lines, which was similar to our observation from the EBVaGC clinical samples." (PMID 32841292, 2020).
mesothelioma (1 paper, 2023). A usually malignant and aggressive neoplasm of the mesothelium which is often associated with exposure to asbestos. "The expression and chromatin analyses at genes such as USP43, HOXA6, HOXA10, and USP18 demonstrate that these genes are downregulated via PRC2-mediated silencing in BAP1-deficient mesothelioma." (PMID 36657447, 2023).
metabolism (1 paper, 2022). "Therefore, for patients with OEMs, the abnormal expression of HOXA10 in OESC reduced the inhibitory effect on the cholesterol synthesis pathway, leading to an increased risk of sterol metabolism diseases." (PMID 35546998, 2022).
metastatic cancer (1 paper, 2020). A carcinoma which has spread from the original site of growth to another anatomic site. "In primary or metastatic cancer, mRNAs IGF2BP3, HOXA9, HOXA10, CEBPG competed with HOXA11-AS mutually, and HOXA10 as well as IGF2BP3 were also continuously up-regulated among normal-primary-metastatic process with significant difference in variance analysis." (PMID 33614509, 2020).
myeloid neoplasm (1 paper, 2020). Proliferation of myeloid cells originating from a primitive stem cell. "Furthermore, results from GSE13159 implicated that the HOXA10 expression was higher in AML than that in other myeloid neoplasms (MDS/CML) and lymphoid malignancies (T-ALL/B-ALL), which indicated that HOXA10 overexpression may be AML-specific signature." (PMID 32571260, 2020).
Obesity (1 paper, 2021). Accumulation of substantial excess body fat. "We also found that H19 and Hoxa10 have the same expression trend, so we next consider whether the competing endogenous RNA (ceRNA) mechanism is involved in the process of obesity affecting fracture healing." (PMID 33471953, 2021).
osteoporosis (1 paper, 2020). A condition of reduced bone mass, with decreased cortical thickness and a decrease in the number and size of the trabeculae of cancellous bone (but normal chemical composition), resulting in increased fracture incidence. "Taken together, the results of our study provide the first clarification of the role of lncRNA OGRU in unloading-induced bone loss through the miR-320-3p/Hoxa10 axis, suggesting an efficient anabolic strategy for osteoporosis treatment." (PMID 32427900, 2020).
Ovarian cyst (1 paper, 2022). The presence of one or more cysts of the ovary. "The methylation rate of HOXA10 CpGs and the correlation between HOXA10 expression and the methylation in eutopic endometrial tissue (EU) and ovarian cyst (OC) were analyzed." (PMID 35546998, 2022).
ovarian endometriosis (1 paper, 2022). A non-neoplastic disorder characterized by the growth of endometrial tissue in the ovaries. "Abnormal cholesterol metabolism in patients with ovarian endometriosis may be related to the abnormal low expression of HOXA10." (PMID 35546998, 2022).
ovarian serous cystadenocarcinoma (1 paper, 2024). A malignant serous cystic epithelial neoplasm arising from the ovary. "In addition, ALKBH5 has been reported to form an ALKBH5–HOXA10 cycle with its upstream factor HOXA10, which enhances cisplatin (CDDP) resistance in ovarian serous cystadenocarcinoma (OV) by mediating JAK2 m6A demethylation." (PMID 38572667, 2024).
ovarian tumor (1 paper, 2019). "Promoter methylation of HOXA10 and HOXA11, which are involved in very early ovarian tumor initiation effectively distinguished normal and malignant ovaries." (PMID 31608277, 2019).
pancreatic adenocarcinoma (1 paper, 2018). "After the OS analysis of these 10 target genes, we found that 4 were OS-associated genes in pancreatic adenocarcinoma: ARHPAG32, HOXA10, CCND1 and CEP55." (PMID 29769534, 2018).
Pancytopenia (1 paper, 2019). An abnormal reduction in numbers of all blood cell types (red blood cells, white blood cells, and platelets). "HoxA9 is co-expressed with additional HoxA proteins, in particular HoxA5, HoxA7, and HoxA10, in immature hematopoietic populations, which likely accounts for the observation that HoxA9-/- mice manifest only mild pancytopenia." (PMID 31120998, 2019).
sarcoma (1 paper, 2022). A usually aggressive malignant neoplasm of the soft tissue or bone. "There is a need for more extensive studies on these genes, as the PTGRD2, CCR3, TOX, and HOXA10 genes are still underexplored in sarcomas." (PMID 36005179, 2022). "Gene expression analysis showed five genes (homeobox A10 (HOXA10), GATA binding protein 3 (GATA3), prostaglandin D2 receptor 2 (PTGDR2), thymocyte selection associated high mobility group box (TOX), and C-C motif chemokine receptor 3 (CCR3)) were dysregulated (p < 0.05) in sarcoma patients." (PMID 36005179, 2022). "Moreover, the reduction in CD4+ T cells and IFN-γ production observed in this study could also indicate that phosphorylation of tyrosine residues did not occur in HOXA10 to inhibit myeloid differentiation but impeded lymphoid differentiation in the sarcoma patients." (PMID 36005179, 2022). "Overall, sarcoma studies related to PTGDR2, CCR3, and HOXA10 are still lacking." (PMID 36005179, 2022).
synovial sarcoma (1 paper, 2025). "Concomitantly, genes activated by SS18::SSX in synovial sarcoma were repressed, including HOX genes HOXC6, HOXA10 as well as SRSF1 and TYMS." (PMID 40804185, 2025).
viral infection (1 paper, 2020). "In relevance to viral infection, MT1F, MT1G, and MT1H proteins exerted some amount of antiviral activity against Hepatitis C viruses (HCV), while HOXA10 was shown to suppress Hepatitis B viruses (HBV) replication." (PMID 32841292, 2020).